CRP (C-reactive protein)
Diseases named in the same sentence as CRP in open-access papers (continued):
Sharing a sentence is not in itself a finding about the gene and the disease.
breast cancer (continued). "The aim of this study is to evaluate the clinical utility of the inflammatory biomarkers serum ferritin and CRP in predicting response to trastuzumab-containing therapy in advanced breast cancer patients." (PMID 23300545, 2012). "The fraction of subjects seeing reduced inflammation, as measured by decreases in CRP, was significantly above fifty percent in the prostate cancer group, the breast cancer group, and the entire study group." (PMID 22963460, 2012). "Breast cancer survivors with higher body fat had higher mean concentrations of CRP and SAA than women with lower body fat." (PMID 22873489, 2012). "Thus, further assessment of the association between NSAID such as aspirin and acute phase proteins in breast cancer survivors may be of value, as lower levels of CRP have been linked with longer survival and NSAIDs have been suggested as an adjuvant treatment for breast cancer." (PMID 22873489, 2012). "In this report, we have demonstrated that both serum ferritin and CRP are strong prognostic factors in advanced breast cancer patients and can predict response to trastuzumab-containing therapy." (PMID 23300545, 2012). "The disease-free survival among breast cancer patients decreased with increasing levels of CRP (log-rank trend, P < 0.001)." (PMID 21639875, 2011). "The principal objective of this study was to determine the relationship between serum IL-6 and CRP levels and staging and prognosis in breast cancer patients." (PMID 21294915, 2011). "Whereas studies that measure CRP after diagnosis and treatment reflect long-term prognosis, studies that measure CRP at the time of diagnosis more likely reflect breast cancer specific survival." (PMID 21639875, 2011). "The largest study so far comprised 700 women treated successfully for early stage breast cancer and found that elevated levels of CRP measured two and a half years after the time of diagnosis were associated with reduced disease-free and overall survival." (PMID 21639875, 2011). "The overall survival among breast cancer patients decreased with increasing levels of CRP (log-rank trend, P < 0.001)." (PMID 21639875, 2011). "The primary objective of this study was to determine the preoperative serum levels of IL-6 and CRP in breast carcinoma, and to correlate them with the staging of the disease and the prognosis." (PMID 21294915, 2011). "In a recent study, the relation between the level of CRP protein in NAF and breast cancer risk as predicted by the Gail model was investigated." (PMID 22276018, 2009). "The aim of the present study was to examine the relationship between clinico-pathologic status, C-reactive protein and albumin concentrations, measured before surgery and cancer-specific survival in patients with invasive primary operable breast cancer." (PMID 17375036, 2007). "In all, 35 of the 43 patients recruited with NSCLC (82%), 15 of the 40 patients with melanoma (37%) and 13 of the 30 (44%) with breast cancer had an APPR defined as a CRP ⩾10 mg l−1." (PMID 15726121, 2005). "The extent of deprivation (Carstairs deprivation index) was directly associated with the magnitude of the systemic inflammatory response (reduced albumin and elevated C-reactive protein, P<0.01) in patients with primary operable breast cancer (n=314)." (PMID 15305191, 2004). "This relationship between deprivation, C-reactive protein and survival remains to be established in patients with primary operable breast cancer." (PMID 15305191, 2004). "Mean CRP was within normal range in healthy controls (2.63 g/dL), while in breast cancer patients, high CRP levels (39.05 g/dL) may refer to a significant association of the inflammatory process with disease progression." (PMID 40791284, 2025). "Regular monitoring of CRP levels in breast cancer patients may assist in evaluating treatment efficacy and detecting recurrence." (PMID 40486605, 2025). "Thus, the level of CRP is statistically significantly higher in the luminal A subtype of breast cancer." (PMID 40699615, 2025).
breast cancer (continued). "Moreover, we also found that this strategy played an important role in reducing the levels of inflammatory biomarkers (TNF-α and CRP) in breast cancer patients." (PMID 40289959, 2025). "A significant increase in CRP levels was noted only in the luminal A subtype of breast cancer." (PMID 40699615, 2025). "In breast cancer patients, both CRP and TNFα increased with time." (PMID 40014780, 2025). "Changes in several biomarkers like myeloperoxidase (MPO), galectin-3 or C-reactive protein (CRP) among others may help predict subsequent CTRCD in breast cancer patients." (PMID 39969700, 2025). "Exercise intervention could reduce the white blood cell count and C-reactive protein (CRP) levels of chemotherapy patients with breast cancer." (PMID 41281288, 2025). "Even though breast cancer is rarely characterized by a significant histologic inflammation, CRP level might be moderately risen indicating a low-grade chronic inflammation." (PMID 40416620, 2025). "When considering individual lifestyle factors, CRP and CAR each mediated 16.58% and 17.20%, respectively, of the associations between diet score and breast cancer risk, while the proportion mediated for physical activity and breast cancer were 12.13% and 11.48%, respectively." (PMID 38360584, 2024). "Higher circulating levels of C-reactive protein (CRP) – a non-specific marker of chronic inflammation – are associated with increased risks of breast cancer, but the epidemiological evidence for other inflammatory markers remains uncertain." (PMID 38363402, 2024). "While there were no notable differences in NLR among the types of anesthesia, the observed disparities in immunoglobulin content and C-reactive protein levels between groups suggest that we cannot dismiss the potential immunosuppressive effects of inhalational anesthesia in breast cancer surgeries." (PMID 39132502, 2024). "Upon further investigation into the associations between components of HLI and breast cancer, we found that CRP and CAR mediated the associations between diet score and physical activity with breast cancer, while MHR mediated the effect of all the components of HLI on breast cancer." (PMID 38360584, 2024). "For each component of HLI, the inverse associations between diet score and physical activity with breast cancer were largely mediated by CAR and CRP, with 16.58% and 17.20% of the overall excess risk for diet score, and 12.13% and 11.48% for physical activity, respectively." (PMID 38360584, 2024). "We have shown that circulating biomarkers of inflammation, hypercoagulability, and endothelial injury, including C-reactive protein (CRP), thrombomodulin (TM), and thrombin–antithrombin complex (TAT), correlated with the risk of DOX-induced cardiotoxicity in breast cancer patients." (PMID 39273682, 2024). "Moreover, breast cancer patients with adipose inflammation have increased insulin, glucose, leptin, triglycerides, CRP, and IL-6 levels as well as decreased HDL and adiponectin levels." (PMID 36670988, 2023). "Recent research has revealed that exercise may significantly exhibit decreased post-operative IGF-1, CRP, TNFα, and Il-6 levels in adult and older adult women with breast cancer." (PMID 37958310, 2023). "A statistically significant increase was noted for NET nucleosomes, thrombin–antithrombin complex (TAT), thrombomodulin (TM), and CRP in breast cancer patients with reduced LVEF > 10% (p < 0.05) compared to the patients with normal LVEF in response to DOX-based chemotherapy." (PMID 37444400, 2023). "Overweight and obese breast cancer patients develop CLS+ and adipose tissue inflammation, which is associated with markers of metabolic derangements, such as increased lipid, glucose and CRP levels in serum." (PMID 36670988, 2023). "Previous studies were identified in this review to show higher or lower levels of CRP in response to chemotherapy in breast cancer patients with no clear association with the onset of CTRCD." (PMID 37444400, 2023).
breast cancer (continued). "Furthermore, clinical analyses were conducted for the sera samples of prostate and breast cancer patients for CRP, cytokines levels (IFN-γ, TNF-α and IL-6), and oxidative stress level markers (MDA and carbonyl contents)." (PMID 37153524, 2023). "According to several studies, raised levels of cytokine-mediated acute phase C-reactive protein, and pro-inflammatory cytokines, including IL-6, IL-1β, and TNF- α are found in breast cancer patients, documenting that breast cancer is associated with inflammation." (PMID 36978815, 2023). "Furthermore, the measurement of the CRP has been proved to have prognostic value in numerous types of cancer, for instance, breast cancer." (PMID 36532648, 2022). "We conducted two studies to examine differences in post-operative physical and mental functioning, pain, fatigue, and systemic inflammatory markers including interleukin (IL)-6, tumor necrosis factor (TNF)-α, and C-reactive protein (CRP) in women with early-stage breast cancer." (PMID 35941136, 2022). "A study on breast cancer patients found a negative association between exercise and IL-6 levels; other meta-analyses have also shown a significant decrease in IL-6 and CRP levels after exercise intervention." (PMID 36482346, 2022). "After adjusting for common confounders, we observed direct associations of GDF-15 with lung cancer risk, NT-proBNP with breast, prostate and colorectal cancers, HbA1C with lung, colorectal, and breast cancer risks, and CRP with lung and colorectal cancer risks." (PMID 34935094, 2022). "Particularly, S1P and CRP promote breast cancer metastasis by influencing tumor cell invasion." (PMID 36473927, 2022). "Lutein and zeaxanthin intakes were associated with decreased CRP levels (SMD −0.3 mg/L; 95% CI −0.45, −0.15) and a dose–response relationship found a favorable 17% decreased risk of breast cancer for every 3000 μg/day increase in lutein and zeaxanthin intake (RR 0.83; 95% CI 0.77, 0.89)." (PMID 35807307, 2022). "It is important to note that, similar to our study, 10 of the 12 studies included in the meta-analysis observed a non-significant association between CRP levels and breast cancer risk, especially after BMI adjustment." (PMID 35430795, 2022). "Also, the result of an analysis of the Women’s Healthy Eating and Living (WHEL) study including 3,402 breast cancer survivors showed a positive significant association between dietary acid load (the PRAL score) and serum C-reactive protein levels." (PMID 36347922, 2022). "Besides, a study in patients with breast cancer found that CRP levels significantly decreased with the improvement of fatigue." (PMID 35273991, 2022). "A combination of the independently-associated markers showed a moderately strong association with the risks of cancer and CVD (HRQ4-Q1 ranged from 1.78[1.36, 2.34] for breast cancer, when combining NT-proBNP and HbA1C, to 2.87[2.15, 3.83] for MI when combining NT-proBNP, HbA1C, CRP and cystatin-C)." (PMID 34935094, 2022). "Similarly, high consumption of dietary fibers is inversely related to the circulating inflammatory markers interleukin 6 (IL-6) and tumor necrosis factor α receptor 2 (TNF-α-R2) in postmenopausal women and C-reactive protein (CRP) in breast cancer survivors." (PMID 35160104, 2022). "A meta-analysis of 12 prospective studies conducted mostly in Caucasian women and focusing on C-Reactive protein (CRP), a non-specific marker of acute inflammation, showed a positive association with breast cancer risk." (PMID 35948877, 2022). "The inflammatory immune parameters, such as FIB, systemic inflammation response index (SIRI), systemic immune-inflammation index (SII), and C-reactive protein (CRP), were included to assess breast cancer prognosis, and parameters with high values were independent prognostic risk factors." (PMID 35774393, 2022). "Moreover, NF-ƙB expression was positively correlated with PTX-3, PCT, CRP, and IL-6 in patients with breast cancer and colon cancer." (PMID 36499628, 2022).
breast cancer (continued). "The significant candidate biomarkers CRP and SAA, the cross-product interaction term of CRP*SAA, and the covariates associated with increased risk of breast cancer relapse were added to a multivariate conditional logistic regression model using both forward and backward variable selection methods." (PMID 33483516, 2021). "In one large prospective study, CRP, fibrinogen, and leukocyte counts were all associated with colorectal, lung, and breast cancer but none were associated with prostate cancer." (PMID 34926085, 2021). "Similarly, subjects with CRP levels >ULN were more likely to have relapsed breast cancer (OR 2.66, 95% CI 1.34–5.28, p = 0.005), while subjects with IL-6 levels >ULN had no increased likelihood of relapsed breast cancer (OR 0.62, 95% CI 0.20–1.90, p = 0.402)." (PMID 33483516, 2021). "Finally, we observed that CRP also amplified killing of breast-cancer tumor cell line SKBR3 by neutrophils through anti-Her2 (trastuzumab)." (PMID 33790888, 2021). "However, elevated CRP has been verified to relate with poor prognosis in a broad variety of cancers such as colorectal cancer, prostate cancer, and breast cancer." (PMID 34336633, 2021). "This prospective, multicenter, open-label, single arm, clinical trial enrolled postmenopausal breast cancer patients (n = 45) with elevated CRP and taking predominantly aromatase inhibitors, to receive a combination of HT, omega-3 fatty acids, and curcumin for 1 month." (PMID 33572626, 2021). "In general, breast cancer survivors had 11% lower CRP levels in winter than in summer." (PMID 33562354, 2021). "The inclusion of cancers other than breast cancer may have influenced the findings for IL-6 and IL-8, but Khosravi did show that CRP and TNF were more sensitive to exercise changes." (PMID 34777343, 2021). "In all other ER‐stratified analyses, there was little evidence of association of other adipokines or CRP with breast cancer outcomes." (PMID 32134113, 2020). "Therefore, we aimed to investigate the effects of exercise on inflammatory cytokines interleukin (IL)-6, IL-18, tumor necrosis factor-α (TNF-α), and C-reactive protein (CRP) in a breast cancer mouse model." (PMID 32309219, 2020). "Fifth, we were unable to examine potential nonlinear associations of adipokines or CRP with breast cancer risk." (PMID 32134113, 2020). "In conclusion, our MR analyses suggest that several adipokines and CRP are unlikely to causally influence breast cancer risk." (PMID 32134113, 2020). "Moreover, cross-sectional studies in breast cancer survivors have shown a correlation between elevation in the pro-inflammatory markers CRP and IL-1 receptor antagonist and persistent post-treatment fatigue." (PMID 32154028, 2020). "Enhanced secretion of CRP in these obese conditions could be involved in breast cancer development and progression, but the molecular mechanisms are only partially understood." (PMID 33614510, 2020). "Further biologic mechanistic study may help to elaborate the sex-hormone interactions with CRP on breast cancer carcinogenesis and the molecular pathways connected to CRP and ER/PR/HER2 receptors." (PMID 33614510, 2020). "Since patients with low levels of NLR or CRP had greater benefit from bevacizumab as compared with those with high levels, these markers may indicate that the microenvironment in breast cancer is likely to afford sufficient efficacy induced by bevacizumab." (PMID 32002126, 2020). "Thus, several studies have showed the effect of high CRP levels as leading to a worse prognosis after the diagnosis of breast cancer." (PMID 33614510, 2020). "A significant reduction in serum CRP in breast cancer patients may demand a higher dose and/or longer duration of statin therapy (e.g. at least 3 months) to demonstrate a similar effect to that observed in CAD patients." (PMID 32849871, 2020). "Of note, a stronger increased risk of breast cancer was observed for the genetic instruments of CRP in HER2/neu-negative breast cancer." (PMID 33614510, 2020).